HAS2 (hyaluronan synthase 2)
Diseases named in the same sentence as HAS2 in open-access papers (continued):
Sharing a sentence is not in itself a finding about the gene and the disease.
cancer (continued). "Mammalian genomes have three different HAS genes (HAS1, HAS2, and HAS3) which are expressed at specific stages and in specific tissues during organ development, aging, wound healing, as well as under normal or pathologic conditions, including diseases such as cancer." (PMID 39766274, 2024). "Finally, we found major differences among the cancer cell lines in their expression of genes involved in glycosylation, including CHST11, CHST13, Ext1, HAS2 and HAS3, which may have an impact on the architectural organization of the spheroids." (PMID 39011470, 2024). "Additionally, our previous work showed that sphingosine 1-phosphate receptor and hyaluronan receptor cooperate to play an important role in cancer lymph-angiogenesis and lymphatic permeability, suggesting that the receptor of SPHK1 product directly interacts with the receptor of HAS2 product." (PMID 33506044, 2021). "Most of the previous studies on HA synthesized by HAS2 and HAS3 were focused mainly on its roles in the ECM and signal transduction, whereas the majority of HAS1 research has focused on prognostic marker studies or expression profiles of HAS1 genes in different cancers." (PMID 29137675, 2017). "Aggressive BC cells express high levels of HA synthase 2 (HAS2) and lower levels of HA synthase 3 (HAS3) compared to non-aggressive cancer cells." (PMID 40443562, 2025). "The levels of HAS2 and HAS3 mRNA (HAS1 was low or absent), were not consistently increased in the carcinomas, and were not significantly correlated with HAS protein or hyaluronan accumulation in individual samples." (PMID 19435493, 2009).
infection (7 papers, 2009 to 2024). The state of being infected such as from the introduction of a foreign agent such as serum, vaccine, antigenic substance or organism. "Hyaluronic acid synthesis has been associated with hormone-, and infection-, induced cervical ripening, a result of increased expression of HA synthase-2 or -3 (Has2/3)." (PMID 29190738, 2017). "Overall, these results demonstrate that endogenous HA produced by HAS2 in fSFs limits the fibroblasts’ ability to enhance infection of CD4+ T cells by HIV." (PMID 33976386, 2021). "Total RNA was extracted from the lungs after 1, 3, 5, 7, 14, and 21 days of infection, and analyzed for HAS1, HAS2, and HAS3 mRNA transcription by reverse transcriptase-polymerase chain reaction (RT-PCR)." (PMID 19876387, 2009). "We demonstrated before that hyaluronan is the major attachment site of both BCG and M. tuberculosis in the infection of A549 cells, which itself produced hyaluronan probably depending on HAS3 and HAS2." (PMID 19876387, 2009). "To see if hyaluronan is present at the site of infection of M. tuberculosis, we assessed the expression of hyaluronan synthases (HAS1, HAS2, and HAS3) in the lungs of BALB/c mice infected with the M. tuberculosis H37Rv strain, using the low-dose aerosol infection model." (PMID 19876387, 2009).
inflammation (3 papers, 2021 to 2025). Aberrant reaction of the microcirculation characterized by movement of fluid and leukocytes from the blood into extravascular tissues. "RNA-seq analysis provided further pathophysiological insights into enhanced eosinophilic airway inflammation when Has2 expression was attenuated." (PMID 35069543, 2021). "Second, this study firstly demonstrated that attenuation of Has2 mRNA affects the severity of pulmonary eosinophilic inflammation and distinctive phenotype airway remodeling using Has2+/− mice." (PMID 35069543, 2021). "The function of HAS1 is not entirely understood, but it may also regulate HAS2 and metabolism of inflammatory matrices post-injury as HAS1-deficient mice develop chronic joint inflammation and severe intra-articular fibrosis following cartilage injury." (PMID 34416923, 2021).
kidney disease (2 papers, 2022 to 2024). "CD44 may directly regulate biological processes such as monocyte aggregation and ECM-receptor interaction, and regulate renal water absorption, signaling and kidney disease/fibrosis through its interaction with HA, HAS2, hyaluronidase, TGF-β1 and FN." (PMID 39411720, 2024). "Although PLPPR1 and SFXN1 genes have not been reported to be associated with kidney disease, the current study found that PLPPR1 and SFXN1 were significantly positively correlated with QDPR and negatively correlated with HAS2 and MYOF." (PMID 35320116, 2022).
HAS2 also shares sentences with these, for which no sentence is quoted: breast (4 papers); cardiovascular disease (2); colon adenocarcinoma (2); ovarian tumors (2); periodic fever syndrome (2); polycystic ovary syndrome (2); prostate tumor (2); acinar adenocarcinoma (1); adenocarcinoma (1); adenomyosis (1); amyloidosis (1); atopic dermatitis (1); benign tumors (1); bowel cancer (1); chondrodysplasia (1); colorectal adenocarcinoma (1); congenital heart disease (1); ductal carcinomas of the breast (1); Fever (1); glomerular disease (1); glomerulosclerosis (1); hepatocellular carcinoma (1); high-grade glioma (1); hyperopia (1); hypertrophic cardiomyopathy (1); idiopathic pulmonary arterial hypertension (1); idiopathic pulmonary fibrosis (1); lung adenocarcinoma (1); lung squamous cell carcinoma (1); lymphocytopenia (1).
A further 15 diseases each share a sentence with HAS2 in 1 paper.